CRP (C-reactive protein)
Diseases named in the same sentence as CRP in open-access papers (continued):
Sharing a sentence is not in itself a finding about the gene and the disease.
coronary stenosis (continued). "In summary, our data show that higher mtDNA 8-OHdG was cross-sectionally associated with increased odds of obstructive CAD, higher degree of coronary stenosis, and higher CRP levels, and prospectively with 1-year adverse clinical outcomes after coronary revascularization." (PMID 32075646, 2020). "Previously, we observed that higher levels of IL-6, but not CRP, were associated with increased prevalence of coronary stenosis ≥50% and greater coronary artery calcification score among HIV-infected men in the MACS." (PMID 30946765, 2019). "However, CRP ≥5 was associated with having significant coronary stenosis, but not CaSc >100, among the study population." (PMID 35476713, 2022). "Inflammation parameters C-reactive protein (CRP), White Blood Cell (WBC) and Neutrophil Lymphocyte ratio (NLR) were higher in the group with clinically significant coronary stenosis (p < 0.001, p = 0.011, p = 0.038)." (PMID 42318145, 2026). "Additionally, the prediction of severe coronary stenosis was higher than NLR, platelet lymphocyte ratio, and CRP levels for SII." (PMID 37664391, 2023). "We identified relevant inflammatory biomarkers (MCP-4, AA, hs-CRP, and TNF-α) of severe carotid artery stenosis and coronary artery stenosis and toxicological effects of inflammatory response on carotid artery stenosis and multivessel coronary artery stenosis in elderly patients." (PMID 34976297, 2021). "This statement is consistent with our results showing that the level of the inflammatory marker plasma C-reactive protein and the expression of proteins contributing to inflammation like COX-2, NFκβ, and 15-LO were increased in the myocardium of patients with coronary stenosis." (PMID 31979197, 2020). "NGAL had a better ability to discriminate severe coronary stenosis than MMP-9, IL-1β, and hs-CRP." (PMID 31387110, 2019). "NGAL had a better ability to discriminate severe coronary stenosis than MMP-9, IL-1β, or hs-CRP." (PMID 31387110, 2019). "And After Bonferroni correction for 16 biomarkers, CRP and HSPCs remained significantly associated with the odd ratio of having CHD vs. no CHD and mild vs. severe coronary stenosis, respectively." (PMID 30737465, 2019). "In the present study, we measured the levels of plasma IL-35, IL-10 and TGF-β1 in CAD patients and their relationship to the other parameters of CAD, including plasma lipoproteins, C-reactive protein (CRP), coronary stenosis and left ventricular ejection fraction." (PMID 23285065, 2012).
endotoxemia (41 papers, 2012 to 2026). "Other research has linked worsening heart dysfunction to endotoxemia, which is characterized by elevated levels of endotoxin, IL-6, and CRP." (PMID 41011058, 2025). "A consistent theme that arose was the effects on low-grade systemic inflammation caused by periodontal bacteraemia/endotoxemia caused by daily activities such as eating and teeth brushing via acute-phase (C-reactive protein, CRP) and neutrophil oxidative stress responses." (PMID 39055690, 2024). "In patients undergoing chronic peritoneal- or hemo-dialysis, positive correlations have been found between lipopolysaccharides from gut bacteria and C-reactive protein levels and subclinical endotoxemia has recently been acknowledged as a relevant cause for inflammation in patients with CKD." (PMID 30181461, 2018). "Nevertheless, the results of the correlation and regression analysis demonstrated the link between increased CRP and endotoxemia in the T1D group in our study, which is in agreement with the published data." (PMID 38137490, 2023). "NF-κB activation and CRP expression are region-specific in response to endotoxemia, and the NF-κB transcription factor subunit p50 interacts with consensus sequence elements of CRP promoter, which implies a cyclic relationship between CRP and NF-κB." (PMID 37893085, 2023). "Researchers in Alexandria, Egypt studied endotoxemia in obese children and adolescents and its possible relationship with insulin, lipid profile and C-reactive protein." (PMID 33924229, 2021). "The pooled DORs of endotoxemia were 3.2 and 5.8 in association with GNBSIs with Escherichia coli and those with Pseudomonas aeruginosa, which were both lower than the DORs of PCT, CRP, and IL-6 derived in our study." (PMID 32076461, 2020). "Using structural equation models, we also tested if the relationship between endotoxemia and cardiometabolic complications was mediated by the latent (unobserved) variable inflammation inferred from the observed biomarkers CRP, TNF-α and IL-6." (PMID 33299020, 2020). "They had elevation of CRP in blood serum, intraalveolar edema of the lung, vacuolar degeneration of hepatocytes, endotoxemia." (PMID 32985516, 2020). "In conclusion, defibrotide infusion enhanced fibrinolysis and reduced C-reactive protein levels during experimental endotoxemia." (PMID 31366975, 2019). "In conditions of endotoxemia, the liver macrophage and monocytes through CRP cytokines stimulate iNOS to increasingly produce NO and peroxynitrites." (PMID 29658815, 2018). "Some meal studies have reported a proinflammatory response, indicated by an increase in endotoxemia, activation of blood leukocytes, induction of nuclear proinflammatory transcription factors and increased CRP." (PMID 22474579, 2012). "This notion was supported by a report showing that increased CRP levels in lipopolysaccharide-induced endotoxemia among healthy volunteers correlate with a rise in total BA concentration where these increased circulating BA metabolites exhibited immunosuppressive properties." (PMID 41244768, 2025). "Moreover, we observed a significant positive correlation between serum LPS and CRP concentrations, suggesting a potential role of endotoxemia in diet-induced meta-inflammation." (PMID 40770069, 2025). "Our second objective was to test, using structural equation models, if the relationship between endotoxemia and cardiometabolic complications was mediated by the latent (unobserved) variable inflammation inferred from the observed biomarkers CRP, TNF-α and IL-6." (PMID 33299020, 2020). "However, several investigations demonstrated the impact of perioperative endotoxemia and subsequent activation of acute-phase mediators, such as IL-6 and CRP, in patients with intestinal, general, vascular and heart surgery." (PMID 24266958, 2013).
endotoxemia (continued). "The functional role of these cytokines in immune responses, as well as the established utility of CRP and SAA as biomarkers of cardiometabolic disease risk, suggest clinically relevant consequences of these observed race-differences in response to endotoxemia." (PMID 23497455, 2013). "Endotoxemia represents a trigger of acute-phase reaction proteins such as IL-6 and CRP." (PMID 24266958, 2013). "Additionally, a mouse model of LPS-challenged endotoxemia was used to explore the zonation and spatial heterogeneity of innate immune function in the liver, revealing that NF-KB (p50) activation and c-reactive protein expression in response to endotoxemia are zone-specific." (PMID 37430371, 2023). "Additional human studies (the GENE evoked endotoxemia study) also confirmed that kynurenine is induced by inflammatory stimuli and is likely up-stream of the inflammatory biomarker CRP, which is also associated, but not causally related, with multiple inflammatory diseases." (PMID 34341450, 2021). "Endotoxemia induced acute SIRS with increased HR, temperature, WBC, CRP and procalcitonin and decreased blood pressure." (PMID 23555024, 2013). "Although our cohort included moderate to severe CDAI patients, inflammatory markers (leukocytes, ESR, CRP) showed no significant group differences, suggesting a possible absence of endotoxemia." (PMID 39860966, 2024). "Interestingly, in terms of microbiota, they found that in T1D patients, Christensenella was negatively correlated with fecal acetate abundance, whereas Subdoligranulum was significantly correlated with plasma markers of endotoxemia LBP and inflammation CRP." (PMID 38034007, 2023). "On the other hand, in this study, short-term HCHFD induced a significant increase in levels of circulating LBP, a marker of endotoxemia, and a non-significant increase in levels of CRP." (PMID 37373776, 2023). "The increased levels of serum C-reactive protein and lipopolysaccharide concentration in patients with IBD highlighted the presence and intensity of systemic inflammation and endotoxemia." (PMID 32766755, 2021). "We then determined the association between shift-work exposure and levels of circulating cytokines, C-reactive protein (CRP), primary LPS-responsive leukocytes (monocytes, lymphocytes, and neutrophils), and LBP (a proxy for LPS) as an indicator of low-grade systemic endotoxemia." (PMID 34948768, 2021). "In feces, Christensenella associated with T1D and correlated negatively with fecal acetate (Spearman r = -0.416, p<0.05), whereas Subdoligranulum correlated significantly with plasma markers of endotoxemia (LBP, r = 0.519, p<0.001) and inflammation (CRP, r = 0.362, p<0.05) in T1D." (PMID 29211757, 2017). "The type of vascular access in HD patients had no influence on endotoxemia, neutrophil function, or oxidative stress, but patients with a central venous catheter had higher CRP, sIL6R and TNFR1 levels." (PMID 27698480, 2016). "Placebo-controlled studies verified that prophylactic oral application of immunoglobulin-enriched colostrum milk preparation diminishes perioperative endotoxemia, prevents reduction of ENC and reduces postoperative CRP-levels, suggesting a stabilization of the gut barrier." (PMID 24266958, 2013). "In patients with endotoxemia, which is followed by increased plasma IL-6 and TNF-alpha levels, plasma YKL-40 increased earlier than serum CRP, which is a nonspecific acute-phase protein synthesized in the liver in response to stimulation, mainly from IL6." (PMID 34579512, 2021).
obstructive sleep apnea (41 papers, 2012 to 2025). "In this context, our study aimed to determine the potential utility of potential biomarkers, such as IL-6, IL-8, IL-10, TNF-α, CRP, and S100B, in the diagnostic process of obstructive sleep apnea (OSA)." (PMID 37762178, 2023). "The Berlin questionnaire for risk of obstructive sleep apnea was used, and the high sensitivity C-reactive protein and glycated hemoglobin levels were evaluated." (PMID 28767909, 2017). "By lowering inflammatory cytokines such as CRP and IL-6, probiotics may help attenuate airway inflammation and collapsibility associated with obstructive sleep apnea." (PMID 40863567, 2025). "There is currently mixed literature on whether CRP may be increased or decreased in obstructive sleep apnea patients and whether treatment with continuous positive airway pressure is associated with improved CRP levels." (PMID 36009133, 2022). "While it appeared that the use of CPAP did not change the level of inflammatory markers after 12 weeks among women with Obstructive Sleep Apnea, it would be of clinical and practical importance to know if changes is hs-CRP and CRP would be associated with weight loss among individuals with OSA." (PMID 33921787, 2021). "This study highlighted a significant association between obstructive sleep apnea (OSA) severity and systemic inflammation, as reflected by elevated C-reactive protein (CRP) and erythrocyte sedimentation rate (ESR) levels." (PMID 40428013, 2025). "Investigate the sleep characteristics of patients with obstructive sleep apnea syndrome (OSAS) comorbidity with panic disorder (PD), exploring its potential association with serum C-reactive protein (CRP) levels." (PMID 37985980, 2023). "It is shown that certain inflammatory parameters including CRP, fibrinogen, IL-6, and Tumor Necrosis Factor-α (TNF-α) are linked with higher cardiovascular risk in patients with obstructive sleep apnea." (PMID 35694268, 2022). "After the analysis of the levels of pro and anti-inflammatory markers (IL-1β, IL-4, IL-6, IL-8, IL-10, Il-15, TNF-α, CRP, α1-GP) in the tonsils, we observed higher levels of markers IL-8 and IL-10 in pediatric patients with obstructive sleep apnea syndrome." (PMID 30213594, 2020). "A study of 30 men with newly diagnosed obstructive sleep apnea and 14 obese controls showed higher CRP in those with obstructive sleep apnea than the obese controls." (PMID 22518315, 2012). "A recent meta-analysis review revealed that CRP/hs-CRP titers are independently linked to Obstructive Sleep Apnea (OSA), yet it is unknown whether there is a link between OSA severity and increased CRP/hs-CRP levels." (PMID 37873776, 2023). "In this perspective, in a group of children affected by SDB, our aim was to investigate MPV, vitamin D and C Reactive Protein (CRP) levels, which had been previously evaluated separately in different studies focused only on Obstructive Sleep Apnea Syndrome (OSAS)." (PMID 27054959, 2016). "Also, a study of 18 men and 4 women showed elevated CRP levels with newly diagnosed obstructive sleep apnea in a multivariate analysis controlling for age, sex, BMI, smoking, alcohol, LDL, and HDL." (PMID 22518315, 2012). "In both pediatric and adult individuals with Obstructive Sleep Apnea (OSA) higher hs-CRP and CRP were observed, compared to controls." (PMID 33921787, 2021). "In this study, we report that CRP is a stronger biomarker of elevated blood pressure and fasting glucose levels than AHI in middle‐aged adults with mild‐to‐moderate obstructive sleep apnea." (PMID 28947597, 2017). "Other studies on obstructive sleep apnea syndrome suggested that patients with obstructive sleep apnea syndrome showed high serum levels of tumor necrosis factor-α (TNF-α), IL-6, CRP, and spontaneous production of IL-6 by monocytes compared with obese control subjects." (PMID 34589489, 2021).
obstructive sleep apnea (continued). "Verify the levels of the inflammatory markers, IL-1β, IL-4, IL-6, IL-8, IL-10, IL-15, TNF-α, CRP and α1-GP, in the tonsils of children with and without obstructive sleep apnea syndrome." (PMID 30213594, 2020).
cellulitis (40 papers, 2009 to 2026). Inflammation of the dermis and subcutaneous tissues caused by a bacterial infection. "Our SIARI score results showed that immunosuppression, infection site, renal function, WBC count, and CRP level were useful for differentiating necrotizing fasciitis from cellulitis among Japanese patients." (PMID 39916636, 2025). "Outcomes included postoperative white blood cell (WBC) count, CRP levels, and complications (seroma, cellulitis, and flap perforation), defined using Centers for Disease Control and Prevention (CDC) guidelines." (PMID 40428897, 2025). "We found higher odds of edema (OR= 1.863, 95%CI, 1.562–2.223), ESR/CRP elevation (OR= 1.797, 95%CI, 1.162–2.779), and cellulitis/lymphadenitis (OR= 1.395, 95% CI, 1.232–1.58) only." (PMID 41001471, 2025). "Patients with necrotizing fasciitis had higher leukocyte counts and blood glucose, hemoglobin A1c, and CRP levels and lower hemoglobin, sodium, and protein levels and erythrocyte counts than those with cellulitis." (PMID 39916636, 2025). "In autoimmune patients, flaps also reduced ESR/CRP elevation and development of cellulitis/lymphadenitis in ECM- and hydrogel-treated patients." (PMID 41001471, 2025). "Antibiotic therapy was initiated in 20 (40%) patients due to elevated CRP and possible concomitant cellulitis." (PMID 34666737, 2021). "After further adjustment for LDL-C, HDL-C, triglycerides, glucose, SBP, hs-CRP, and HOMA-IR, the associations between BMI categories and cellulitis-related hospitalization were attenuated but remained significant (Model 2)." (PMID 31262086, 2019). "A high CRP level also occurs in general cellulitis, but the mean CRP level of 28.1 mg/dL in the OCNF cases was extremely high, which reflects the severe infection and tissue destruction in OCNF." (PMID 31815018, 2019). "Most importantly, a strong difference in the CRP levels was observed between the two conditions: Patients with cellulitis exhibited an increased CRP of 49 mg/dl (median, range 1 to 278) which was well above normal values of healthy controls." (PMID 26196941, 2015). "This is not surprising as the presenting symptoms, signs and investigations are consistent with cellulitis; fever and pain are usually present and investigations show leucocytosis, neutrophilia and a raised serum CRP." (PMID 24392172, 2014). "However, using CRP in combination with other factors such as hemodynamic instability and abdominal wall cellulitis does improve the discriminatory profile (AUC 0.89)." (PMID 41602873, 2026). "While CRP is a well-established marker of systemic inflammation, it may not fully capture the complexity of the inflammatory response in cellulitis patients." (PMID 40620438, 2025). "In addition, a new study has elaborated the usefulness of CRP and differential (neutrophil) blood count for differentiating between erysipelas and S.aureus-mediated cellulitis." (PMID 33413190, 2021). "We chose 948 patients with CRP values for the cellulitis group." (PMID 28611889, 2017). "However, leukocyte counts are not part of the paediatric laboratory risk indicator for necrotising fasciitis, developed to differentiate cellulitis from necrotising fasciitis: Only C-reactive protein and sodium levels below 135mmol/L were found to be of relevance." (PMID 30975101, 2019). "Moreover, as was the case with the herein presented patient, laboratory parameters such as CRP and CK could aid in early NF recognition since levels are higher in patients with NF than in those with cellulitis." (PMID 24711984, 2014). "Cellulitis: In cases of cellulitis, POC VBG, POC CRP, POC CBC, and POCUS are required for patient assessment." (PMID 38434607, 2024). "High values of C-reactive protein (CRP) and creatine kinase (CK) indicate NSTI and, for example, provide evidence against cellulitis." (PMID 21083873, 2010). "The patient was afebrile, and his white blood cells and C-reactive protein were normal, unlikely to be cellulitis." (PMID 40922886, 2025).
cellulitis (continued). "These patients were also found to have a greater inflammatory response than patients without a history of cellulitis, as demonstrated by a higher peak C-reactive protein level, higher peak leukocyte count, and longer duration of fever after hospital admission." (PMID 39163102, 2024). "The most used inflammatory laboratory parameters, like elevated WBC and CRP, are also present in other soft tissue infections like cellulitis, making these parameters non-specific in the diagnosis of NF." (PMID 37134092, 2023). "One individual was hospitalized for cellulitis and was included as a negative control due to increased C-reactive protein." (PMID 34605900, 2021). "In comparing laboratory values between the cellulitis and NF groups, we found statistically significant differences between the WBC (p<0.0001), serum sodium level (p<0.0001), creatinine level (p<0.0001), glucose level (p<0.0001) and CRP level (p=0.0035)." (PMID 28611889, 2017). "POC CRP and CBC can be used to rule out cellulitis and infection as potential causes." (PMID 38434607, 2024). "Additionally, while factors such as elevated C-reactive protein (CRP) levels, body mass index (BMI), and the use of corticosteroids are commonly associated with increased thrombosis risk, their specific roles in cellulitis-related thrombosis have not been clearly defined." (PMID 40620438, 2025). "For the one case not misdiagnosed as cellulitis pain but not fever was reported, and the WCC, neutrophil count and CRP were within the normal range." (PMID 24392172, 2014). "For example, in a patient with leg swelling, we may rule out cellulitis or DVT using POC D-dimer, CRP and CBS." (PMID 38434607, 2024).